ERCC1 (ERCC excision repair 1, endonuclease non-catalytic subunit)
Diseases named in the same sentence as ERCC1 in open-access papers (continued):
Sharing a sentence is not in itself a finding about the gene and the disease.
lung cancer (continued). "Previous studies have shown that ERCC1 induction by cisplatin was dependent on the MAPK pathway and that blocking ERK1/2 activation decreased cisplatin-induced ERCC1 protein levels in lung cancer and melanoma cell lines." (PMID 29156754, 2017). "In particular, an ERCC1-XPF endonuclease inhibitor (IC50 < 1 μM), with specificity against another endonuclease and, despite only showing ̃2-fold enhanced sensitivity to cisplatin, potentiated cisplatin activity in a lung cancer xenograft model." (PMID 28903417, 2017). "It has been reported that high expression levels of ERCC1 and RRM1 may reduce the response rate and survival rate in lung cancer patients treated with cisplatin and/or gemcitabine." (PMID 27800005, 2016). "To examine the gene expression levels for ERCC1 and PCYT1A in different cancer patient tissue samples, we performed qPCR analysis on OriGene’s lung cancer qPCR TissueScan cDNA array panel, which contains cDNA from 24 lung cancer patient tissues." (PMID 23171216, 2012). "In the International Lung Cancer Trial (IALT) adjuvant chemotherapy significantly prolonged survival among patients with ERCC1 negative tumors but not among ERCC1-positive patients." (PMID 19452042, 2008). "However, a major limitation has been the use of relatively non-specific ERCC1 antibodies for immunohistochemistry in previous studies, including in a large lung cancer clinical trial." (PMID 31405143, 2019). "Furthermore, after observing that EGCG could inhibit ERCC1/XPF and, along with Pro-EGCG, could sensitize lung cancer cells to cisplatin in vitro, we assessed the effects of combination treatment with cisplatin and Pro-EGCG in vivo." (PMID 30400270, 2018). "In the present study, we found that two rSNPs (ERCC1 rs3212924 and XPC rs2229090) were associated with PFS and one rSNP (ERCC4 rs1799798) associated with OS of NSCLC patients, and these associations were not previously reported for lung cancer." (PMID 28878296, 2017). "A polymorphism in the 3′ UTR of ERCC1 (not the exon 4 RFLP studied here) has been associated with glioma and SCCHN and two XPA polymorphisms are associated with lung cancer." (PMID 12865926, 2003).
non-small cell lung carcinoma (93 papers, 2008 to 2024). A group of at least three distinct histological types of lung cancer, including non-small cell squamous cell carcinoma, adenocarcinoma, and large cell carcinoma. "This study aimed to evaluate the association of the single-nucleotide polymorphisms (SNPs) rs3212986 and rs11615 within the ERCC1 gene in non-small cell lung cancer (NSCLC) patients." (PMID 39431656, 2024). "Similar studies reported that ERCC1-associated nucleotide excision repair pathways are involved in cisplatin resistance in non-small-cell lung cancer." (PMID 37296596, 2023). "Particularly, the ERCC1 rs11615 T allele was found to be a risk factor for developing non-small cell lung cancer." (PMID 35627777, 2022). "The ERCC1 rs11615 genotype was found to be significantly associated with treatment response to chemotherapy in patients with advanced non-small-cell lung cancer." (PMID 33029487, 2020). "High ERCC1 expression has been linked with poor response to cisplatin therapy in a number of tumors, including non-small-cell lung carcinoma, head and neck, and ovarian cancer." (PMID 33291532, 2020). "Studies have linked the expression of excision repair cross-complementation group 1 (ERCC1) gene to chemoresistance as well as to poor survival in many types of cancer such as non-small-cell lung cancer, ovarian and gastric tumors." (PMID 32167697, 2020). "Non-small cell lung cancers (NSCLC) with excision repair cross-complementation group 1 (ERCC1) deficiency were exquisitely sensitive to NAMPT inhibitors, in vitro and in vivo." (PMID 32010616, 2019). "As the limiting factor in nucleotide excision repair, the expression level of ERCC1 has been shown to be associated with survival outcome in non-small-cell lung cancer." (PMID 28100260, 2017). "High ERCC1 expression at the mRNA or protein level has been linked in many studies with poor response to chemotherapy: non-small cell lung carcinoma; squamous cell carcinoma; and ovarian cancer." (PMID 28903417, 2017). "The A allele of the ERCC1 C8092A polymorphism was found to be associated with shortened survival in patients with non-small-cell lung cancer and advanced colorectal cancer, respectively, treated with platinum-based chemotherapy." (PMID 26019482, 2014). "Moreover, excision repair cross-complementing group 1 gene (ERCC1) rs3212986 GG homozygosity and rs11615 T allele were associated with a higher risk of developing non-small cell lung cancer (NSCLC) in the Polish population." (PMID 35069899, 2022). "A study investigating the role of three SNPs of ERCC1 in the clinical outcome of non-small-cell lung cancer (NSCLC) showed that the TT genotype of ERCC1 rs11615 and the AA genotype of rs3212986 polymorphisms were associated with an increased risk of death from NSCLC." (PMID 33029487, 2020). "There are studies which show that polymorphisms in genes involved in DNA repair (like ERCC1: excision repair 1 gene) may influence the non-small cell lung cancer prognosis." (PMID 33273562, 2020). "Using a similar approach, one recent retrospective study analyzed resected tumor tissue immunohistochemistry for ERCC1 to determine associations between tumor expression of the protein and tumor characteristics or survival in patients with non-small cell lung cancer." (PMID 25191856, 2014). "Also, RRM1 was correlated with expression of the DNA repair protein ERCC1 and was associated with better outcome of early-stage non-small-cell lung cancer." (PMID 23922955, 2013). "Overexpression of ERCC1 is associated to the resistance to platinum-based chemotherapy, which has been demonstrated in various kinds of cancers, including esophageal cancers, non-small cell lung cancers, and bladder cancers." (PMID 23209813, 2012). "Results of studies on genetic polymorphisms of ERCC1 gene in DNA repair pathway which may affect response to platinum-based chemotherapy and survival in patients with non-small cell lung cancer are conflicting." (PMID 20677561, 2010).
non-small cell lung carcinoma (continued). "Interestingly, a study in patients with non-small-cell lung cancer on a docetaxel/cisplatin regimen showed the opposite association, that is, longer survival of the patients with T/T genotypes by the ERCC1 Asn118Asn polymorphism compared to patients with C/T and C/C genotypes." (PMID 26019482, 2014). "Clinical studies have revealed that ERCC1 expression levels serve as a reliable predictor of treatment outcomes in non-small cell lung cancer patients, with high ERCC1 expression correlating with a 50% reduction in progression-free survival." (PMID 39596466, 2024). "Overexpression of ERCC1-XPF has been linked with poorer prognosis and reduced response to chemotherapeutics in various cancers, including ovarian, testicular, non-small cell lung cancer (NSCLC), and squamous cell carcinoma." (PMID 39335146, 2024). "A study explored the expression pattern of ERCC1in 51 patients with non-small cell lung cancer undergoing surgery to understand the correlation between ERCC1 expression and patient survival." (PMID 36338712, 2022). "In 2005, Simon’s analysis included 51 patients who were operated on for non-small cell lung cancer and determined their ERCC1 expression." (PMID 32397531, 2020). "In advanced non-small cell lung cancer, the ERCC1 expression has a significant prognostic value and its high level is associated with a longer survival in patients who do not receive chemotherapy after a complete resection." (PMID 32397531, 2020). "High expression of XP genes, like ERCC1, has also been correlated with poor therapy response in different cancer entities like e.g. non-small cell lung cancer, esophageal cancer, breast cancer, colorectal cancer, as well as head and neck cancer." (PMID 29416673, 2018). "This problem is illustrated by the attempts to validate ERCC1 as a predictive biomarker for chemotherapy for non-small cell lung cancer, which failed because the commercial antibody used for ERCC1 did not perform as expected." (PMID 29144383, 2017). "ERCC1 overexpression indicated worse survival in osteosarcoma and non-small-cell lung cancer (NSCLC) patients receiving cisplatin-based chemotherapy." (PMID 28977987, 2017). "We then determined a synergistic effect compared to cisplatin alone, particularly when both XLF and ERCC1 were knocked down because ERCC1 positive-tumors predict cisplatin resistance in non-small-cell lung cancer and squamous cell carcinoma." (PMID 28526069, 2017). "Excision repair cross-complement 1 (ERCC1) is a 15-kb human nucleotide excision repair gene with already documented importance in developing resistance to platinum compounds in NSCLC (non small cell lung cancer), ovarian, colorectal and cervical cancer." (PMID 28659181, 2017). "Thirty-three studies of platinum-based chemotherapy in non-small-cell lung cancer using ERCC1 were identified." (PMID 26775588, 2016). "As a case study we evaluated how a particular predictive biomarker, ERCC1, was assessed in research on platinum-based chemotherapy in non-small-cell lung cancer and what motivated the choice of procedure." (PMID 26775588, 2016). "High levels of mRNA and protein of the factors of NER ERCC1 and XPD were reported to be associated with resistance to cisplatin therapy in some tumours (e.g. non-small-cell lung cancer)." (PMID 26019482, 2014). "Among these genes, the most studied is ERCC1 gene, mostly focused on the therapy of non-small cell lung cancer (NSCLC) and esophageal cancer." (PMID 25452763, 2014). "Some previous studies have reported that ERCC1 expression is a predictive factor for survival after chemotherapy in advanced non-small cell lung cancer, bladder cancer, gastric cancer." (PMID 25175730, 2014). "In non-small cell lung cancer, ERCC1 gene copy number increases were detected by FISH in 25.5% of samples a finding comparable to the 27.0% reported in the present study, although the FISH probe design and scoring differed substantially." (PMID 24144331, 2013).
non-small cell lung carcinoma (continued). "In patients with completely resected non-small-cell lung cancer, ERCC1-negative tumours showed greater benefit from cisplatin-based adjuvant chemotherapy compared with ERCC1-positive tumours." (PMID 19259093, 2009). "Currently, available antibodies such as 8F1 cannot discriminate between these isoforms and thus cannot guide therapeutic decision-making regarding cisplatin combined therapy in patients with non-small-cell lung cancer; this requires specific detection of the unique functional ERCC1-202 isoform." (PMID 39516666, 2024). "In addition, it has been reported in many studies that the overexpression of ERCC1 reduces the overall- and event-free survival rate in non-small cell lung cancer, head and neck cancer, gastric cancer, esophageal cancer, and breast cancer undergoing CRT." (PMID 37296596, 2023). "In addition, in the study of ERCC1 in postoperative non-small cell lung cancer, it was found that the expression of ERCC1 mRNA was negatively correlated with chemotherapy efficacy and survival time of patients." (PMID 37400750, 2023). "Increased ERCC1 is correlated with platinum resistance in many cancers, including ovarian, nasopharyngeal, cervical, head and neck squamous carcinoma, lung adenocarcinoma, non-small cell lung cancer, and gastric cancer." (PMID 36551731, 2022). "One retrospective analysis showed a relationship between increased ERCC1 mRNA or protein expression levels and resistance to cisplatin-based chemotherapy in many types of advanced tumors, including non-small cell lung cancer (NSCLC), esophageal cancer, and colon cancer." (PMID 36230725, 2022). "For example, ERCC1 expression levels have an inverse correlation with either response to platinum-based adjuvant chemotherapy or survival in patients with ovarian cancer, colorectal cancer, and non-small cell lung cancer (NSCLC)." (PMID 35999268, 2022). "Other research teams have reported high correlations between low ERCC1 expression and in vitro sensitivity to cisplatin in malignant cervical cancer cell lines, testicular cancer, and malignant effusions collected from non-small cell lung cancer patients." (PMID 36230725, 2022). "EGCG is a compound capable of inhibiting the activity of the ERCC1/XPF protein in non-small cell lung cancer cell lines, blocking the intrastrand crosslink repair, and thus enhancing the cytotoxic activities of cisplatin, preventing proliferation and increasing cellular death." (PMID 33330091, 2020). "ERCC1 expression predicts efficacy in patients with non-small cell lung cancer or head and neck squamous cell carcinoma, who have received platinum-based concurrent chemoradiotherapy; meanwhile, patients with low ERCC1 expression often show better treatment response and survival." (PMID 29179456, 2017). "An inverse correlation of ERCC1 (one of the nucleotide excision repair pathway components) with response either to platinum therapy or to survival was clearly established in ovarian cancer, non-small cell lung cancer and colorectal cancers." (PMID 25885449, 2015). "It has been demonstrated in several clinical studies that ERCC1 messenger RNA expression in various types of cancer, including ovarian, colorectal, gastric and esophageal cancer, as well as non-small cell lung cancer (NSCLC), is correlated with clinical resistance to platinum agents." (PMID 23426424, 2013). "According to some studies, increased ERCC1 expression could be associated with resistance to cisplatin-based therapy in HCC, similar to what is observed in non-small cell lung carcinoma." (PMID 23162604, 2012). "Moreover, the relationship between the expression of ERCC1 and tumor response or survival has also been demonstrated in esophageal cancer patients treated with chemoradiotherapy and non-small cell lung cancer treated with cisplatin-based adjuvant chemotherapy." (PMID 21426588, 2011).
non-small cell lung carcinoma (continued). "The relation between ERCC1 expression and resistance to platinum compounds had been found by some clinical studies in patients with advanced-stage gastric, ovarian, colorectal, esophageal, and non-small-cell lung cancers." (PMID 21426588, 2011). "A total of 10 open studies are listed in this search for "ERCC1" and "non-small cell lung cancer"." (PMID 21152077, 2010). "Notably, recent clinical evidence suggests that ERCC1 levels predict response to platinum-based therapies in non-small cells lung cancer, small cell lung cancer, esophageal cancer, head and neck cancer, bladder cancer and testicular cancer." (PMID 20470425, 2010). "Positive expression of ERCC1 was significantly higher in group of non-small cell lung cancer (NSCLC), highly differ- entiated and the smokers less than 400 (P < 0.05), positive expression of GST-pi was significantly higher in group of non-smok- ers and NSCLC (P < 0.05)." (PMID 20673515, 2010). "Interestingly, in a recent study, non-small-cell lung cancer (NSCLC) patients homologous for the ERCC1 118 (excision repair cross-complementing 1) exhibited a significantly better survival." (PMID 19478952, 2009). "Interestingly, in the present study, ERCC1 mRNA levels were lower in patients with good PS, which has also been found in non-small-cell lung cancer patients." (PMID 18362936, 2008). "ERCC1 rs735482 is involved in the identification and removing platinum-induced intra-strand adducts in DNA, and is resistant to platinum-based chemotherapy in many cancers, including non-small cell lung cancer, ovarian cancer, bone tumor, and colorectal cancer." (PMID 35905230, 2022). "A Chinese study reported that a polymorphism of ERCC1 could influence the response to platinum-based chemotherapy, whereby the ERCC1 C/C genotype is a favorable factor for the platinum-based chemotherapy response in Chinese patients with non-small-cell lung cancer." (PMID 33029487, 2020). "siRNA-mediated knockdown of ERCC1, XPF, and ERCC1–XPF reduced the rate of cisplatin adduct repair in non-small cell lung cancer, ovarian cancer, and breast cancer cell lines." (PMID 36551731, 2022). "ERCC1 protein is proposed as an important biomarker for clinicians to predict whether a certain patient population with non-small cell lung carcinoma (NSCLC) will respond to cisplatin chemotherapy." (PMID 23171216, 2012). "ERCC1 has been investigated as a biomarker in both adrenocortical carcinomas and advanced non-small cell lung cancer and did not offer prognostic or treatment selection benefits." (PMID 36176755, 2022). "We conducted the present study to investigate the association between two polymorphisms of excision of repair cross-complementing group 1 (ERCC1), the key component of the NER pathway, and the clinicopathological features of patients with non-small cell lung cancer (NSCLC)." (PMID 31245210, 2019). "The present study aimed to investigate the association between epidermal growth factor receptor (EGFR) gene mutations and excision repair cross-complementing protein 1 (ERCC1) and ribonucleotide reductase subunit M1 (RRM1) mRNA expression in non-small cell lung cancer (NSCLC) tissue." (PMID 25667646, 2015). "Negative or weak expression of ERCC1 was associated with better systemic chemotherapeutic response in HNSCC, bladder cancer and non small cell lung cancer (NSCLC)." (PMID 24077122, 2013). "In addition to its predictive role for cisplatin-based chemotherapy, ERCC1 has significant prognostic value because high ERCC1 expression is associated with longer survival in patients who do not receive chemotherapy after complete resection for non-small cell lung cancer." (PMID 22616552, 2012). "Similarly, non-small cell lung carcinoma (NSCLC) displayed a correlation between CDDP resistance and ERCC1 levels." (PMID 20470393, 2010).
non-small cell lung carcinoma (continued). "In stage IV, non-small-cell lung cancer patients treated with cisplatin-based chemotherapy, ERCC1 protein expression did not predict response, whereas ERCC1 mRNA expression was significantly associated with response." (PMID 18362936, 2008). "Moreover, miR-495 could reverse cisplatin resistance in non-small cell lung cancer by regulating the expression of the drug resistance genes ABCG2 and ERCC1 and directly targeting UBE2C 3′-UTR, affecting cells growth, invasion, and metastasis." (PMID 34935899, 2022). "It indicated that ERCC1 expression could predict clinical outcomes of chemotherapy in cancers such as non-small cell lung cancer, bladder cancer, and gastric cancer but not in stage II-III CRC." (PMID 25175730, 2014). "Interestingly, curcumin and emodin, which are natural anthraquinone derivatives found in the roots and rhizomes of numerous plants, were found to enhance cisplatin-induced cytotoxicity via downregulation of ERCC1 and inactivation of ERK1/2 in non-small cell lung cancer." (PMID 23299493, 2013). "Moreover, patients with completely resected non-small-cell lung cancer and ERCC1-negative tumors appear to benefit from adjuvant cisplatin-based chemotherapy, whereas patients with ERCC1-positive tumors do not." (PMID 21385444, 2011).